LINC02820 (long independently transcribed non-coding RNA 2820)
Synonyms: lnc-ALX1-2
Gene: Long non-coding RNA gene on chromosome 12 (85,317,964 to 85,594,711, forward strand). Ensembl gene ENSG00000258815.
Diseases named in the same sentence as LINC02820 in open-access papers:
LINC02820 is named in the same sentence as 1 disease in open-access papers, as found by Europe PMC text mining. Sharing a sentence is not in itself a finding about the gene and the disease. The quoted sentences say what the papers report.
tumor (1 paper, 2025). "Together with our overexpression results, these gain‐ and loss‐of‐function studies support the essential role of LINC02820 in promoting ESCC tumor growth and metastasis." (PMID 40416600, 2025). "To validate the tumor‐promoting function of LINC02820 in vivo, we established xenograft models using LINC02820‐knockdown KYSE410 cells." (PMID 40416600, 2025).